SMAD7 (SMAD family member 7)
Diseases named in the same sentence as SMAD7 in open-access papers (continued):
Sharing a sentence is not in itself a finding about the gene and the disease.
cancer (continued). "miR-182 silencing leads to SMAD7 upregulation on TGFβ treatment and prevents TGFβ-induced EMT and invasion of cancer cells." (PMID 27996004, 2016). "While miR-182 suppression led to SMAD7 induction on TGFβ treatment and abolished TGFβ-induced EMT phenotypes, simultaneous treatment with the SMAD7 inhibitor restored cancer cell responses to TGFβ." (PMID 27996004, 2016). "Western blot and immunofluorescence analyses showed that miR-182 inhibition resulted in upregulation of SMAD7 protein, and suppressed the changes of EMT markers in response to TGFβ in the cancer cells." (PMID 27996004, 2016). "Mothers against decapentaplegic homolog 7 (SMAD7) inhibits the transforming growth factor-β (TGF-β) signaling pathway, which regulates carcinogenesis and cancer progression." (PMID 28070019, 2016). "Early studies describe upregulation of TGF-β in invasive HCC, low levels of TβRII in HCC with intrahepatic metastasis and elevated levels of Smad7 in late stage HCC and other cancers." (PMID 23991075, 2013). "It is known that SMAD7 functions as an intracellular antagonist of transforming growth factor beta (TGF-beta) signaling and is frequently unregulated in various cancers." (PMID 21569311, 2011). "In addition, the PI3K/AKT pathway-related genes including FXYD3, SMAD7, and ITGB8, are involved in stem cell-like properties in various cancer types, which are transcriptionally regulated by SETD541–47." (PMID 37963940, 2023). "On the other hand, the increased expression of SMAD7 could prevent the activation of TGF-β and inhibit EMT in cancer cells." (PMID 37834191, 2023). "They activate cancer cell signaling pathways and transcription factors, including IGF1/α6β4 complex, FGFR2, TIMP, DNA replication and mTOR signaling, Smad7, KLF4, and TBX2, and downstream proto-oncogenes such as MYC, MET, and CDK1, which facilitate cancer progression." (PMID 37046676, 2023). "Also, simulation results succeeded to reproduce the behavior of SMAD7, TGFβ, LIF, and CXCL12 molecules in both cancer cell and CAF." (PMID 36171274, 2022). "SRPX2 also exhibited excellent antifibrosis effect via TGFβR1/SMAD3/SRPX2/AP1/SMAD7-positive feedback loop, indicating that SRPX2 might be a therapeutic target for inflammation and cancer-related inflammation for future cancer therapeutics." (PMID 35935582, 2022). "Cancer cell lines originating from same organ often gathered in the same cluster, such as C2 [COAD/READ-STAD-PAAD], a group of digestive system cancers whose common features were the high expression of CNKSR1, FOLH1, ADGRG1, SMAD7, LRATD1 and MVP." (PMID 32874774, 2020). "Moreover, we also observed a positive correlation between Smad7 and HDAC6 mRNA, and c-Jun and HDAC6 mRNA in several various cancer forms." (PMID 32888405, 2020). "Our data suggest that RAC1B induces SMAD7 by promoting its deubiquitination and establishes this Smad as one of RAC1B’s downstream effectors in negative regulation of ALK5 and TGFβ1-induced cell migration in mesenchymal-type carcinoma cells." (PMID 32545415, 2020). "Moreover, SMAD7, the transcriptional target and negative regulator of TGF-β signaling, upregulated TGF-β and inducing SMAD7 transcription prevented TGF-β-induced EMT and invasion of cancer cells." (PMID 31195692, 2019). "MicroRNA-182 targets SMAD7 to potentiate TGF-β-induced EMT and metastasis of cancer cells." (PMID 31681406, 2019). "In addition to its direct contribution in cancer cell invasion, COPS5 is known to regulate TGF-β signaling by binding to Smad7, which is the important signaling pathway for both metastasis and EMT." (PMID 29755680, 2018). "Moreover, it was reported that some microRNAs targeting Smad7 promote TGF-β–mediated EMT and invasion of cancer cells." (PMID 29180690, 2017). "SMAD7 is a TGF-β inhibitor and inhibits EMT process in various cancer cells." (PMID 28107197, 2017).
cancer (continued). "TGFβ stimulation usually elicits sustained morphological and behavioural changes of cancer cells, despite the SMAD7-mediated negative feedback of the pathway." (PMID 27996004, 2016). "Unlike in cancer cells, TGFβ treatment of these normal cells failed to induce the expression of miR-182, and thus an obvious increase of SMAD7 protein was observed following TGFβ stimulation." (PMID 27996004, 2016). "The role of SMAD7 in cancer progression is not uniform, as overexpression of SMAD7 can lead to both favorable and poor prognoses." (PMID 27957497, 2016). "Under these circumstances, the SMAD7-mediated negative feedback loop of TGFβ signalling was disrupted in these cancer cell lines, leading to sustained responses of EMT." (PMID 27996004, 2016). "Third, we only assessed the association of SMAD7 polymorphisms with CRC risk, because there were not sufficient studies conducted on other cancers." (PMID 28070019, 2016). "Here, however, we show that TGFβ treatment induces SMAD7 transcription but not its protein level in a panel of cancer cells." (PMID 27996004, 2016). "With forced expression of SMAD7, miR-182 was no longer able to boost the cancer cell invasion after TGFβ stimulation." (PMID 27996004, 2016). "Silencing of SMAD7 reduced the ability of IL-1α to enhance the stimulating effect of PSC conditioned medium on the migration of the carcinoma cells compared to conditioned medium from non-silenced PSCs." (PMID 27473228, 2016). "For example, genes with Motif 1 in Molecular Mechanisms of Cancer pathway include MAPK1, BRAF, SMAD2, FZD5, FZD8, NOTCH1 and LRP1, whereas genes with Motif 2 and/or Motif3 in the same pathway include LRP5, LRP6, MDM2, CTNND1, SMAD3, SMAD4 and SMAD7." (PMID 26040697, 2015). "Both phosphorylation of Smad2 and induction of SMAD7 by TGF-β were observed in TβRII-expressing cancer cells, but not in control SCLC cells that expressed green fluorescent protein (GFP) alone (H82-GFP cells and H345-GFP cells)." (PMID 27462425, 2015). "Further investigation revealed that Smad7 acted as a scaffold protein to facilitate TGF-β-induced activation of p38 and subsequent apoptosis and was required for induction of apoptosis by the anti-cancer agent 2-Methoxyestradiol." (PMID 24317436, 2013). "Smad7 plays inhibitory roles in the transforming growth factor beta (TGF-β) signaling pathway which is involved in many cellular processes and has an important role in cancer development and progression." (PMID 23560096, 2013). "This work highlights the role of Smads in determining the sensitivity to BMPs and shows that upregulation of Smad7 in cancer cells is sufficient to escape the negative effects of BMPs." (PMID 23049692, 2012). "Analysis of the mechanisms by which SMAD7 regulates CRC cell behavior revealed that SMAD7 binds the promoter of STAT3, and the AS-induced knockdown of SMAD7 reduces STAT3 mRNA and protein expression in CRC cells, suggesting a role for SMAD7 in the control of STAT3-dependent cancer cell behavior." (PMID 39001432, 2024). "In HUVECs, miR-27b-3p not only suppressed cell proliferation and migration via Smad7-mediated modification of TGF-β but also sensitized breast cancer cells to several anti-cancer treatments both in vivo and in vitro, suggesting the probable involvement of miR-27b-3p in cancer biology." (PMID 37854681, 2023). "In this context, it is noteworthy that, in addition to cancer cells, CRC samples include fractions of additional cell types (e.g., immune cells and stromal cells) that could express variable levels of Smad7 and/or Stat3 mRNA, thus contributing to the RNA transcripts measured in such samples." (PMID 36291778, 2022). "Smad7 is a critical negative regulator of TGF-β signaling and may play a dual role as a proliferation promoting factor or a metastatic suppressor in different human cancers." (PMID 33255941, 2020).
cancer (continued). "Moreover, some recent studies show that circular RNAs, such as circCACTIN and circCCDC66, also affect cancer progression by regulating the TGF-β pathway, and circular RNA cESRP1 can increase the chemosensitivity of cancer cells by inducing Smad7 and blocking the TGF-β pathway." (PMID 33114183, 2020). "Given the role of Smad7 in inhibiting TGF-β signaling, a possible explanation of these opposite effects could be due to the different functionality of this pathway among distinct cancer types." (PMID 24317436, 2013). "If not inhibited by endogenous (e.g., Smad6 and Smad7) or pharmacological (e.g., galunisertib or SB-431542) agents, increased TGF-β-Smad2/3 signaling activity in cancer cells induce cancer cell migration and invasion." (PMID 39724753, 2024). "The antisense strand of Smad7 upstream was transcripted into lncRNA-Smad7, which specifically suppresses TGF-β-induced apoptosis of cancer cells, but TGF-β-induced EMT was not affected." (PMID 35736633, 2022). "Human CC specimens express high levels of Smad7 in both cancer cells and LPMC and CC cell lines contain much more Smad7 than non-tumoral intestinal epithelial cell lines." (PMID 33920230, 2021). "This study confirmed decrease in SEC13 expression with all cancer stages (II, III, IV); while SMAD7 tended to be especially highly expressed in GC patients with stage IV, which could explain the significant negative correlation between SEC13 and SMAD7." (PMID 35449150, 2022). "In addition, it is also noticed that SMAD7 overexpression failed to completely block cancer cell TGFβ responses as revealed by SBE activity, osteoclast differentiation and PTHLH induction, implying a SMAD7-independent mechanism for the oncogenic role of miR-182 and the TGFβ response of cancer cells." (PMID 27996004, 2016).
infection (22 papers, 2006 to 2024). The state of being infected such as from the introduction of a foreign agent such as serum, vaccine, antigenic substance or organism. "Caspase recruitment domain family member 10 (CARD10) and Mothers against decapentaplegic homolog (SMAD7) were uniquely up-regulated in the multiple infection group." (PMID 37910477, 2023). "As expected, while MDA231 cells infected with Ad-CMV-GFP (control) adenovirus showed strong migration in response to rhTGF-β1 treatment, SMAD7 overexpression by infection with Ad-CMV-Flag-SMAD7 adenovirus reduced this effect." (PMID 38105247, 2023). "In parallel, mice infected with Ad-Smads2/3/4 exhibited lower circulating insulin levels under fasting conditions, whereas Ad-Smad7 infection further increased the levels of circulating insulin (left)." (PMID 29700281, 2018). "In contrast to the effects of Ad-Smad7 infection, liver lysates from HFD-fed mice infected with Ad-Smads2/3/4 displayed lower levels of phospho-S6 Ser240/244 in response to fasting compared with the levels in uninfected HFD-fed mice." (PMID 29700281, 2018). "The gene expression time course in primary and secondary infection showed that Smad7 expression, which is at basal level in primary infection, increased rapidly during secondary infection." (PMID 25341656, 2014). "More specifically, although Smad7 can suppress the TGF-β signaling pathway to initiate infection tolerance, it can also promote immunity triggered through the IFN-γ signaling pathway." (PMID 25341656, 2014). "Smad7 during secondary infection was found to suppress TGF-β signaling, leading to attenuated inhibition of immune cells." (PMID 25341656, 2014). "In the reciprocal inhibition of TGF-β and IFN-γ, Smad7 is the key component responsible for polarizing responses toward either immunity or tolerance to infection." (PMID 25341656, 2014). "The time course of Smad7 expression showed a significant increasing trend of inhibitory Smad7 expression during secondary infection, suggesting that TGF-β signaling is suppressed in secondary infection relative to primary infection." (PMID 25341656, 2014). "The mRNA expressions of TLR3, TGFβ3 and SMAD7 in the lungs following infection with Pigeon04 were negatively correlated with viral replication." (PMID 21826229, 2011). "Initial localization studies indicate that mCMV infection changed the cell-specific expression of FN, NF-κB2, RelA, RelB, and Shh and Smad7 proteins." (PMID 18371224, 2008). "We therefore examined Smad7 expression levels in ECs by semi-quantitative RT-PCR upon infection of adenovirus expressing constitutively active (ca)ALK1, caALK5, or noninfected cells that were stimulated with TGF-β." (PMID 16571110, 2006). "Interestingly, the expression of Smad7 dramatically decreased after 7 wpi, whereas Smad4 continued to increase after infection." (PMID 36474240, 2022). "Alpha-smooth muscle actin (α-SMA), collagen I, collagen III, TGF-β1, Smad2, Smad3, and Smad4 showed a significant increase in mitochondrial RNA (mRNA) and protein expression compared with the control group at 7 and 9 weeks post-infection (wpi), while an opposite effect on Smad7 was observed." (PMID 36474240, 2022). "Moreover, we found that BMP2 effectively upregulated Smad7 expression at 3 and 5 days after infection." (PMID 33588941, 2021). "Consistent with this, and in contrast to the effects of infection with Ad-Smad7, HFD-fed mice infected with Ad-Smads2/3/4 exhibited lower lipogenesis, liver triglyceride, circulating total cholesterol, high-density lipoprotein (HDL)-cholesterol, and low-density lipoprotein (LDL)-cholesterol." (PMID 29700281, 2018). "Furthermore, we compared the expression profile of Smad7 over time during primary and secondary infection to see if there was a significant change in between infections." (PMID 25341656, 2014).
infection (continued). "However, in secondary infection with a lethal pathogen dose, increased Smad7 expression suggests that the immune response is triggered to defend against the invading pathogen; thus, the pathway responsible for infection tolerance is inhibited in this phase." (PMID 25341656, 2014). "Furthermore, the discovery that Smad7 interacted with Acvr1b only during secondary infection suggests that TGF-β controls immune responses via a SMAD-dependent pathway." (PMID 25341656, 2014). "Therefore, the role of Smad7 in secondary infection suggests that attenuated suppression of immune cells, which enables the adaptive immune response to defend against high-dose secondary infection." (PMID 25341656, 2014). "Consistent with this, we observed that Ad-Smads2/3/4 infection caused a significant upregulation of the insulin receptor substrate (IRS)-phosphoinositide 3-kinase (PI3K) pathway, which may contribute to enhanced glucose uptake, whereas the IRS-PI3K pathway was downregulated by Ad-Smad7 infection." (PMID 29700281, 2018). "The difference in Smad7 expression between the primary and secondary infections may indicate that after initial low-dose infection, the zebrafish immune system was able to tolerate the invading pathogen, thereby shifting the immune response toward infection tolerance." (PMID 25341656, 2014). "The list includes hsa-miR-4775, already predicted to target SARS-CoV-2 3′-UTR by Yousefi and colleagues and which also regulates Smad7 protein in the TGF-beta pathway, thus modulating the immune response after infection." (PMID 34198800, 2021). "At 8 weeks post-infection, expression of SMAD6 and SMAD7 was significantly up-regulated in the Mtb-infected/Fe-supplemented animals, compared to placebo-treated rabbits." (PMID 31382404, 2019). "At 8 weeks post-infection, expression of IL10, NOS2, and SMAD7 was significantly up-regulated in the Fe-supplemented animals." (PMID 31382404, 2019). "Ad-Smads2/3/4 infection considerably decreased serum proinflammatory proteins when compared with uninfected HFD-fed mice, whereas Ad-Smad7 infection increased the serum levels of proinflammatory proteins." (PMID 29700281, 2018). "Smad7, a member of the inhibitor SMADs, was identified to be a key protein in TGF-β signaling involved in secondary infection only." (PMID 25341656, 2014). "In primary infection, the SMAD protein Smad2 was found to interact with Acvr1b; whereas in secondary infection, Smad2, Smad3, and Smad7 were found to interacted with Acvr1b." (PMID 25341656, 2014). "Neither SMAD7 nor FGF2 expression levels were distinct following infection and did not appear to explain the differences in cytopathic effect seen in the current studies." (PMID 34372702, 2021). "These loci exhibited negative (ELN, SASH1, and SMAD7) and positive (CDSN, NCSTN, and PEX7) relationships between minor allele frequency and infection severity, with no overarching pattern evident in control loci lacking association with mange severity." (PMID 33664786, 2021). "In addition, Ad-Smads2/3/4 infection significantly increased in vitro insulin-stimulated 2-deoxy-glucose uptake in WAT and muscle, whereas Ad-Smad7 infection had the opposite effect." (PMID 29700281, 2018). "As expected, Ad-Smads2/3/4 infection enhanced ketone body production and ketogenic gene expression under fasting conditions when compared with uninfected HFD-fed mice, but Ad-Smad7 infection had the opposite effect." (PMID 29700281, 2018). "In this study, SMAD7 expression was maintained at a similar level at the chronic stage of infection, since SMAD7 does not appear in the list of DEGS of T3vsT2." (PMID 27661612, 2016). "Smad7, an I-SMAD protein, was found to be important in TGF-β signaling in secondary infection only." (PMID 25341656, 2014). "Smad7 protein was found to interact with Acvr1b during secondary but not primary infection." (PMID 25341656, 2014). "However, Smad7, an I-SMAD, was found to interact with Acvr1b during secondary, but not primary, infection." (PMID 25341656, 2014).